PTH (parathyroid hormone)
Diseases named in the same sentence as PTH in open-access papers (continued):
Sharing a sentence is not in itself a finding about the gene and the disease.
Hypocalcemia (continued). "Low vitamin D levels reduce calcium absorption, which in turn upregulates parathyroid hormone release, osteoclastogenesis, and bone resorption to prevent hypocalcemia, thus, increasing bone loss." (PMID 36618706, 2022). "Hypocalcemia causes excessive secretion of phosphorus and parathyroid hormone, leading to chronic renal failure (CRF) and end-stage kidney disease (ESRD)." (PMID 35370668, 2022). "Hypocalcemia with PTH elevation can be caused by increased phosphate load, vitamin D deficiency, vitamin D metabolism defect, renal dysfunction, hypomagnesemia, genetic mutations resulting in end-organ resistance to PTH, or critical illness." (PMID 36440223, 2022). "PHP is a group of endocrine disorders with end-organ hormone resistance to parathyroid hormone which manifests with hypocalcemia causing neurologic symptoms (e.g., seizures and tetany), hyperphosphatemia, and elevated parathyroid hormone." (PMID 34693503, 2022). "We aimed to determine if early post-surgery PTH and calcium levels can be used for the early identification of patients at risk for symptomatic hypocalcemia." (PMID 35566513, 2022). "In the regression model higher preoperative PTH (OR = 1.011, p = 0.041) and 25-hydroxyvitaminD deficiency (OR = 0.343, p = 0.011) significantly predicted transient postoperative hypocalcemia." (PMID 34564834, 2022). "Pseudohypoparathyroidism (PHP) is a heterogeneous group of endocrine disorders characterized by renal resistance to parathyroid hormone (PTH), causing hypocalcaemia, hyperphosphataemia and elevated circulating PTH levels." (PMID 35643636, 2022). "At the age of 4 years, he experienced a generalized seizure associated with severe hypocalcemia (5.8 mg/dL, normal range 8.7–10.3 mg/dL) and high levels of serum carboxyl terminal fragments of PTH (C-PTH) (1.0 ng/mL, normal range < 0.5 ng/mL)." (PMID 35497370, 2022). "PTH resistance is characterized by elevated parathyroid hormone (PTH) levels, hypocalcemia, hyperphosphatemia and it is classically associated with GNAS locus genetic or epigenetic defects." (PMID 35846276, 2022). "Postoperative hypoparathyroidism (POH) is the most common and important complication and is associated with decreased serum parathyroid hormone (PTH) levels, hypocalcemia and hyperphosphatemia." (PMID 35937810, 2022). "POD1 PTH levels ≥ 15 pg/ml along with calcium ≥ 2.0 mmol/l are associated with low risk of symptomatic hypocalcaemia, and represent a safe criterion for discharge of most patients without calcium supplementation." (PMID 35247092, 2022). "Based on this assumption, viral-induced CaSR over-expression would render parathyroid glands hypofunctional, causing PTH impairment and hypocalcemia; nevertheless, studies on this regard are still missing." (PMID 36467702, 2022). "Hypoparathyroidism (HP) is a rare metabolic disorder and causes hypocalcemia because parathyroid hormone secretion is inadequate to mobilize calcium from bone and reabsorb calcium from kidney and gut." (PMID 34224552, 2022). "As a result, calcium remained bound in the patient’s bones rather than in the serum, causing the parathyroid gland to respond to this perceived hypocalcemia by secreting abnormally high levels of PTH." (PMID 35145817, 2022). "The majority of the 16 patients who presented with postoperative hypocalcemia had a very high preoperative PTH (p) and/or a vitamin D deficiency, which can be explained by the hungry bone syndrome." (PMID 36268338, 2022). "Hypocalcemia was found in 82.8% of patients, hyperphosphatemia in 57.2%, vitamin D insufficiency or deficiency in 60%, and altered parathyroid hormone values in 48.6%." (PMID 35442270, 2022). "Several strategies have been studied regarding the early identification of patients at risk for postoperative hypocalcemia, including PTH and calcium measurements from 10 min to 24 h." (PMID 35566513, 2022).
Hypocalcemia (continued). "The low plasma levels of parathormone (PTH) associated with hypoparathyroidism can cause hypocalcemia, adversely affecting clinical outcomes and the quality of life of the patient." (PMID 36561508, 2022). "Blood testing showed severe hypocalcemia with a high PTH level as well as vitamin D deficiency (serum 25OHD level was 12.9 ng/ml)." (PMID 36465610, 2022). "Our data confirm the idea that the reduced PTH secretory reserve in patients with 22q11.2DS results in a predisposition toward hypocalcemia in the presence of stress or increased calcium demand." (PMID 35432203, 2022). "This presumption is consistent with the observation that cinacalcet, a calcimimetic that suppresses synthesis and secretion of PTH, reduced tubular Ca reabsorption and caused hypocalcemia as it lowered [PTH] in CKD stages G3 and G4." (PMID 35913960, 2022). "PTH levels performed on POD1 would appear to reliably predict patients at low risk of symptomatic hypocalcaemia." (PMID 35247092, 2022). "In this study, we proposed our preoperative schedule and observed an obvious effect in preventing postoperative hypocalcemia in patients with bilateral thyroid cancer, especially for those at risk of low postoperative PTH levels." (PMID 36091150, 2022). "Postoperative follow-up showed a positive relationship between the onset of hypocalcemia and vitamin D deficiency, and an inverse correlation between PTH concentration and postoperative hypocalcemia." (PMID 36268338, 2022). "A 25-year-old female first presented with a generalized seizure associated with hypocalcemia (2.1 mg/dL), hyperphosphatemia (10.5 mg/dL), and elevated serum intact PTH levels (524.8 pg/mL) at the age of 4 years." (PMID 35497370, 2022). "Several studies suggest that a within-the-normal-range PTH preoperatively and a low PTH in the early postoperative period can identify patients at risk for developing hypocalcemia after thyroidectomy." (PMID 35566513, 2022). "Low calcitriol contributes to hypocalcemia and, together with the established hyperphosphatemia, causes increased PTH release and secondary hyperparathyroidism." (PMID 36293083, 2022). "The main laboratory characteristics of PHP are hypocalcaemia and hyperphosphatemia associated with elevated PTH levels, which frequently encompass additional heterogeneous clinical features, referred to as Albright’s hereditary osteodystrophy (AHO)." (PMID 36213284, 2022). "Although vitamin D deficiency is one of the main causes of hypocalcaemia, inappropriate levels of parathyroid hormone (PTH) are a contributing factor." (PMID 35992140, 2022). "VD deficiency with hypocalcemia and decreased calcium absorption from diet leads to enhanced PTH secretion, which results in increased renal calcium reabsorption and osteoclastic bone resorption." (PMID 33804453, 2021). "As an example, while low d[Ca] can be a good choice for patients with adynamic bone disease to avoid vascular calcification, it can also induce hypocalcemia and stimulate PTH secretion, leading to high risk of arrhythmias and cardiac arrest." (PMID 33107900, 2021). "Secondary hyperparathyroidism is a frequent complication of chronic kidney disease and it is caused due to decreased vitamin D synthesis, parathyroid (PTH) skeletal resistance, hyperphosphatemia, as well as hypocalcemia." (PMID 34098899, 2021). "Hypocalcemia, hyperphosphatemia, and low or undetectable PTH levels can cause muscle symptoms, such as cramps, seizures, paresthesias and numbness, life-threatening arrhythmias, laryngospasm, and bronchospasm." (PMID 34746197, 2021). "Though multiple studies showed that the absolute value of postoperative serum parathyroid hormone (PTH) was an accurate predictor of high-risk hypocalcemia in thyroidectomy patients, cutoff value was variant." (PMID 33762946, 2021). "The results also showed that low pre-RAI serum calcium and PTH values were risk factors for hypocalcemia five days post-RAI by multivariate regression analysis." (PMID 34122347, 2021).
Hypocalcemia (continued). "This suggests that calcitriol supplement in patients with RDP >70% is associated with fewer incidences of clinical hypocalcemia and patients’ requirement for i.v. calcium, as well as elevated PTH level." (PMID 33762946, 2021). "Given its role in the regulation of calcium and PTH levels, vitamin D deficiency was presumed as a potential risk factor of postoperative hypocalcemia." (PMID 34956363, 2021). "Currently, early measurement of PTH in the postoperative period is widely accepted as the best way to identify patients at risk of hypocalcemia following total thyroidectomy." (PMID 33599211, 2021). "The association of hypocalcemia with an inappropriately low (or low-normal) PTH and hyperphosphatemia leads to the diagnosis." (PMID 34820344, 2021). "As a result, hypocalcemia occurs and parathyroid hormone (PTH) is stimulated, causing hyperparathyroidism." (PMID 34445034, 2021). "This is expected as PTH exerts an osteoclastic function on the bone to correct hypocalcemia secondary to vitamin D deficiency." (PMID 34580590, 2021). "Critical illness hypocalcemia is multifactorial and is attributed to vitamin D deficiency, abnormal PTH secretion and action, circulating catecholamines, medication adverse effects, and citrated blood transfusion." (PMID 33542868, 2021). "Intraoperative PTH assay has been suggested to have value in predicting and identifying the patients being at risk of post-thyroidectomy hypoparathyroidism and hypocalcemia." (PMID 34429957, 2021). "The measurement of PTH levels post-thyroidectomy allows for early risk assessment of hypocalcaemia and are an integral part of local guidelines in identifying and appropriately managing affected patients." (PMID 34164240, 2021). "If PTH is elevated (the expected response to hypocalcemia), and 25(OH)D is low, the patient has vitamin D deficiency." (PMID 33542868, 2021). "A single 1-hour post-thyroidectomy parathyroid hormone level has been validated to risk stratify patients into low-risk and high-risk groups for developing post-operative symptomatic hypocalcemia." (PMID 34394008, 2021). "Considering age, performance of central neck lymphadenectomy, diagnosis of malignancy and PTH postoperatively, multivariate analysis only showed an association between the latter and post-total thyroidectomy hypocalcemia." (PMID 31492617, 2021). "The monitoring of hypocalcaemia improved significantly; 83.3% (n=5) of patients who were at an intermediate risk of hypocalcaemia (PTH 0.6-1.6) had 12 hourly calcium monitoring for 48 hours compared to 22.2% prior to the QI project." (PMID 34164240, 2021). "Pseudohypoparathyroidism (PHP) is a rare disease caused by resistance to parathyroid hormone (PTH), which results in hypocalcaemia, hyperphosphataemia and elevated PTH level." (PMID 33422028, 2021). "Although other parameters frequently associated with hypocalcemia have initially shown a relationship to this outcome, only postoperative PTH remained significant in multivariate analysis." (PMID 31492617, 2021). "Practicing oncologists should also consider routine calcium measurements since hMg can cause hypocalcemia through impaired PTH release and function." (PMID 34938893, 2021). "We have identified a high baseline PTH as a risk factor for necessitating further titration of cinacalcet and proposed a baseline PTH > 30 pmol/L for initiating at full dose of 60 mg/day, though patients given 60 mg/day are at greater risk of hypocalcaemia." (PMID 34647901, 2021). "In multivariate analysis only parathyroid hormone in postoperative (p = 0.02) was associated with post-total thyroidectomy hypocalcemia." (PMID 31492617, 2021). "To identify the cause of postoperative hypocalcemia after a total thyroidectomy we suggest incorporating postoperative PTH measurements into the standard biochemical follow-up after a total thyroidectomy." (PMID 34659111, 2021).
Hypocalcemia (continued). "This secondary hypocalcemia is probably caused by inhibition of the parathyroid gland by the hypomagnesemia, resulting in low levels of parathyroid hormone which eventually results in hypocalcemia." (PMID 32302086, 2021). "Mithramycin associates with hypocalcemia by blocking osteoclast function and PTH action on gut and bone directly, or by causing vitamin D resistance." (PMID 32509580, 2020). "Contrary to hyperparathyroidism, hypoparathyroidism, which refers to the impaired secretion of PTH due to the irreversible parathyroidectomy, radiation damage, and congenital disabilities, is the leading cause of chronic hypocalcemia." (PMID 33015068, 2020). "The association of age, gender, preoperative PTH level, Ca level, and PTH level reduction on postoperative day 1 with the incidence of postoperative hypocalcemia after total thyroidectomy with CLND was identified." (PMID 32802056, 2020). "In conclusion, single‐dose administration of NPSP795 has been shown to cause dose‐dependent increases in PTH and to ameliorate the hypocalcemia in an ADH1 mouse model." (PMID 33103030, 2020). "It leads to the development of secondary hyperparathyroidism, in which high levels of PTH caused by chronic hypocalcemia and calcitriol deficiency accompany hyperphosphatemia." (PMID 32823917, 2020). "Calcilytics have the potential to treat autosomal dominant hypocalcemia type 1 (ADH1), which is caused by germline gain‐of‐function CaSR mutations and leads to symptomatic hypocalcemia, inappropriately low PTH concentrations, and hypercalciuria." (PMID 33103030, 2020). "Pseudohypoparathyroidism (PHP) is a heterogeneous group of endocrine disorders characterized by renal resistance to parathyroid hormone (PTH), causing hypocalcaemia, hyperphosphatemia and elevated circulating PTH levels." (PMID 30968677, 2020). "Female patients with large tumor size and >71.00% PTH reduction on postoperative day 1 posttotal thyroidectomy with CLND had a high risk of transient hypocalcemia." (PMID 32802056, 2020). "Our present study illustrated that PTH level reduction, female gender, and tumor diameter were risk factors for postoperative hypocalcemia in patients who underwent total thyroidectomy with CLND." (PMID 32802056, 2020). "Asymptomatic female patients with bilateral CLND and a 71.00% PTH level reduction were at a high risk of transient hypocalcemia." (PMID 32802056, 2020). "The focus in management involves an aggressive lowering of PTH by treating hyperphosphatemia, hypocalcemia, and vitamin D deficiency." (PMID 33062583, 2020). "Denosumab commonly causes hypocalcemia and hyperparathyroidism since it inhibits osteoclast activation, reduces calcium release from bone and increases PTH levels as a compensatory mechanism." (PMID 32244607, 2020). "To simplify, PHP, which is associated with hypocalcemia, hyperphosphatemia, and raised PTH concentrations, leads to the dysfunction of G proteins which can alter renal calcium resorption thus decreasing GABAergic inhibition." (PMID 32715645, 2020). "ADH1 (OMIM #601198) has been reported in association with >70 different CaSR mutations, and is characterized by hypocalcemia, hyperphosphatemia, hypomagnesemia, inappropriately low or normal PTH concentrations, and a relative or absolute hypercalciuria." (PMID 31820785, 2020). "The causes of hypocalcemia include oversecretion of PTH, VD deficiency, decreased dietary intake, hypoproteinemia, hypomagnesemia drug interactions, and so on." (PMID 32589164, 2020). "Our present study documented that the threshold of postoperative day 1 PTH reduction was a reliable independent risk factor for predicting transient hypocalcemia in patients who underwent a total thyroidectomy with bilateral and/or ipsilateral CLND." (PMID 32802056, 2020). "This hypocalcemia was associated with a concomitant increase in plasma Mg and a decrease in PTH levels, bringing up the key role of Mg in the regulation of PTH secretion." (PMID 33282857, 2020).
Hypocalcemia (continued). "It was found that vitamin E deficiency (VED) diet caused hypocalcemia in the first month, elevated parathyroid hormone (PTH) level in the second month and reduced bone calcium content in L4 vertebra in the third month in female rats." (PMID 31963885, 2020). "Hypocalcemia consequent to low levels of circulating parathyroid hormone is the hallmark of hypoparathyroidism." (PMID 33062471, 2020). "Although rare, severe hypocalcemia after cinacalcet has been associated with higher baseline serum PTH levels." (PMID 32621588, 2020). "PTH ≤ 15.5 significantly increases the risk of developing hypocalcemia, and prophylactic ≥1000 mg elementary calcium is recommended for these patients." (PMID 32555278, 2020). "Vitamin D deficiency associated with hypocalcaemia due to a decrease in calcium absorption from the diet is known to result in increased PTH secretion from the parathyroid." (PMID 30393837, 2019). "Serum magnesium was severely low at 0.35 mmol/L and was associated with a mild hypocalcaemia and suppressed parathyroid hormone (PTH)." (PMID 31448104, 2019). "In CKD progression, both hyperphosphatemia and 1,25-dihydroxy vitamin D deficiency cause hypocalcemia and stimulate parathyroid hormone (PTH) secretion from the parathyroid gland, called SHPT." (PMID 31879808, 2019). "Decreased 1,25-dihydroxyvitamin D (1,25-vitD) levels and hypocalcemia associated with reduced or elevated parathyroid hormone (PTH) levels have been reported in small samples of patients with established AKI." (PMID 30971270, 2019). "In patients with vitamin D deficiency, serum hypocalcemia stimulates parathyroid hormone production." (PMID 30815231, 2019). "These patients express activating mutations in CaSR, or in G protein 11 (GNA11), which cause hypocalcemia, inappropriately low PTH levels, and moderate hyperphosphatemia." (PMID 31619668, 2019). "The main causes of hypocalcemia in infants with asphyxia include increased phosphate load due to cellular damage, increased calcitonin production, renal failure, and decreased PTH secretion." (PMID 31320908, 2019). "Diagnostic evaluation revealed severe hypocalcemia, hyperphosphatemia and elevated serum intact PTH level." (PMID 31856822, 2019). "Differential diagnoses in this patient who presented with symptomatic hypocalcemia were hypoparathyroidism, secondary hyperparathyroidism due to long standing vitamin D deficiency, PTH resistance due to magnesium deficiency and pseudohypoparathyroidism." (PMID 31856822, 2019). "Inappropriately low (insufficient) circulating PTH levels, which in adults occurs mainly after thyroid surgery, is the most common cause of hypocalcemia." (PMID 29694629, 2018). "In CKD, PTH synthesis is increased in response to both 1,25D deficiency and hypocalcemia, then PTH stimulates renal CYP27B1 expression to rescue the 1,25D level." (PMID 30513912, 2018). "In brief, an increase of FGF-23 in CKD follows 1,25D deficiency and hypocalcemia, thereby increasing the PTH level and results in SHPT in CKD." (PMID 30513912, 2018). "The present study found very similar results in the 10-year follow-up: 41.94% of the sample had high PTH, 82.86% had vitamin D deficiency, 12.5% had hypocalcemia, and most patients had normal magnesium and phosphorus levels." (PMID 30539982, 2018). "Both phosphate burden and 1,25D deficiency cause hypocalcemia and stimulate PTH secretion from PTG, called SHPT." (PMID 30513912, 2018). "The decay of PTH levels in samples collected before and 1 hour after surgery has been associated with the occurrence of hypocalcemia (B)." (PMID 29694629, 2018). "SHPT refers to the excessive secretion of parathyroid hormone (PTH) by the parathyroid glands in response to hypocalcemia and associated hyperplasia of the glands." (PMID 29301445, 2018).